CGAS (cyclic GMP-AMP synthase)
Diseases named in the same sentence as CGAS in open-access papers (continued):
Sharing a sentence is not in itself a finding about the gene and the disease.
cancer (continued). "The presence of cGAMP in cancer cells was confirmed as expected in MDA231, and the increase in DNA leakage from the nucleus by Dox treatment was considered to increase cGAMP production by cGAS." (PMID 34445736, 2021). "In cancer cells, the emergence of micronuclei promotes the cellular invasion ability by sustaining a cell-autonomous process such as the cyclic GMP–AMP synthase (cGAS)–stimulator of interferon genes (STING) pathway." (PMID 34526560, 2021). "Thus, the cGAS‒STING pathway may act as a double-edged sword that, on the one hand, offers the first line of defense against infection, but on the other hand, causes detrimental consequences to the system, such as cancer and metabolic dysfunction, when inappropriately activated." (PMID 34665236, 2021). "Therefore, targeting the cGAS-STING pathway can alleviate autoimmune symptoms and be a potential drug target for treating cancer." (PMID 34867409, 2021). "Active PKR, TBK-1, cGAS/STING, and RIG-I all have the potential to restrict Δγ134.5 replication, and the heterogenous inhibition of these pathways across cancer types provides a possible explanation for the replication variability observed with first-generation Δγ134.5 oncolytics." (PMID 34372614, 2021). "To evaluate whether these DNA species in the cytosol contribute to constitutive cGAS activation and the induction of STING unresponsiveness, we first labelled cGAMP-responsive and unresponsive cancer cell lines for dsDNA and RNA:DNA hybrids in the cytosol." (PMID 33790360, 2021). "In contrast, we observed comparable induction of ISGs during fractionated irradiation of cancer cell lines, irrespective of cGAS or STING expression." (PMID 33964942, 2021). "Therefore, targeting the cGAS-STING signaling pathway to activate innate immunity and enhance the immune function provides great potential for cancer treatments." (PMID 34867409, 2021). "Chronic activation of noncanonical NF-κB and inflammatory pathways downstream of cGAS-STING in cancer cells with CIN has been shown to promote migration and metastasis." (PMID 34518527, 2021). "In addition, cGAS and STING can serve as a bridge connecting innate immunity and adaptive immunity and regulate the occurrence and development of malignant tumors." (PMID 34867409, 2021). "In addition to induction of Type I IFN expression, activation of the cGAS-STING pathway upregulates the expression of NK cell receptor NKG2D ligands that can lead to the recognition and destruction of cancer cells by NK cells and T cells." (PMID 34579759, 2021). "Besides the cGAS and STING antimicrobial role, recent reports have expanded their functions to cancer, including other cellular roles like repair of DNA and autophagy." (PMID 34519260, 2021). "Finally, cGAS itself can be translocated into the nucleus to inhibit PARP1 repair of double-stranded DNA breaks, promoting cancer metastasis." (PMID 34905701, 2021). "Thus, agonists are being developed to restore and to enhance cGAS-STING activity and the subsequent antitumor immune response in cancer treatment." (PMID 34944052, 2021). "Data suggest that in gastrointestinal diseases, cGAS-STING activation is key for the onset of colitis and CRC, while in other cancer types such as prostate, the accumulation of cytosolic DNA increases disease progression from non-malignant to hyperplasia to stage II." (PMID 34072037, 2021). "The inhibition of autophagy through chemical inhibitors as well as the genomic silencing of cGAS or SQSTM1 could suppress the growth and survival of cancer cells, and induced DNA damage could increase the sensitivity to these inhibitors." (PMID 34123836, 2021). "Emerging lines of evidence have suggested that the cGAS/STING pathway plays a pivotal role in regulating DNA damage response and genomic instability, which is involved in the progression of multiple diseases including cancer." (PMID 35265630, 2021).
cancer (continued). "In addition, two indirect regulators targeting the cGAS-STING pathway have been tested clinically for pharmacologic metabolic research and cancer treatment." (PMID 34867409, 2021). "Recent studies have shown that cGAS recognizes not only non-self but also self-derived cytoplasmic DNA fragments in cancer cells produced by irradiation-induced DNA damage." (PMID 35008367, 2021). "cGAS-STING signaling exerts antitumor functions in cancer cells both in an autonomous and nonautonomous manner." (PMID 32854711, 2020). "The activation of the cGAS-STING pathway transfer signals from the binding of ligand and receptor to the transcriptional level in the nucleus by phosphorylating second messengers, which renders STING a potential target for cancer biotherapy." (PMID 32887628, 2020). "HER2 expression has recently been found to suppress antiviral defenses and antitumor immunity as a result of HER2 signaling through its intracellular domain, which interferes with cyclic GMP-AMP synthase-stimulator of interferon genes (cGAS-STING) pathway and prevents cancer cell death." (PMID 32349330, 2020). "Further, cGAS was dispensable in DCs but not cancer cells for optimal CD8+ T cell-mediated cancer immunosurveillance, indicating DC activation was not occurring via nucleic acid sensing." (PMID 33238631, 2020). "Due to the ubiquity of cytosolic DNA in chromosomally unstable cancer cells, cGAS-STING and the non-canonical NF-κB pathway were found to be activated." (PMID 32774773, 2020). "An important caveat is that intratumoral cGAS-STING expression, as determined via bulk RNA-Seq in most of these studies, comprises expressed cGAS and STING from both host (stromal and immune cells) and cancer cells." (PMID 32774773, 2020). "Stimulator of interferon genes or cyclic-GMP-AMP synthase is expressed widely in a broad spectrum of cells including immune, non-immune, cancer cells." (PMID 32411126, 2020). "Therefore, we systematically analyzed the expression, molecular cascade, and functions of TLR3, RIG-I, MDA5, LGP2, cGAS, and STING in human cancer cells." (PMID 33490069, 2020). "Surprisingly, DMXAA only augments murine cGAS-STING signals, instead of that signals in humans, which may account for the dysfunction of treating cancer patients in clinical trials." (PMID 32887628, 2020). "The cGAS-STING signaling inhibits this premature senescence and progression towards cancer." (PMID 33643304, 2020). "Interestingly, knockdown of cGAS (cyclic GMP-AMP synthase) along with induction of mitotic arrest in HeLa and U2OS cancer cells clearly resulted in increased micronuclei formation and chromosome missegregation." (PMID 32284536, 2020). "Further investigation of the molecular details of the cGAS-STING pathway in different types, stages, and microenvironments of cancers might help to address this knowledge gap." (PMID 32532954, 2020). "The cGAS-STING pathway is the central cellular cytosolic double-stranded DNA (dsDNA) sensor, allowing innate immune to respond to infections, inflammation, and cancer." (PMID 32571374, 2020). "Moreover, most of the cGAS-STING agonist clinical trials are conducted with CPIs (pembrolizumab, ipilimumab and nivolumab) for cancer biotherapy." (PMID 32887628, 2020). "Future studies should address the possibility that the cGAS/STING pathway may contribute to development of the low‐adherent phenotype and thereby play a role in survival and radiotherapy‐resistance of cancer cells." (PMID 30919591, 2019). "Therefore, it’s of great importance to re-stimulate cGAS-cGAMP-STING pathway and promote T-cell proliferation in cancer immunotherapy." (PMID 31120925, 2019). "Additionally, these compounds provoke cytosolic DNA fragments that are recognized by cGAS following the activation of the pathway, emphasizing the strong synergy between DNA damaging agents and cGAS-STING signaling in clearing cancer cells." (PMID 31658669, 2019).
cancer (continued). "Among internal sensing systems, the cyclic GMP-AMP synthase–stimulator of interferon genes (cGAS-STING) pathway can mediate the response to cytosolic DNA and has attracted interest as a target of therapy in diseases such as cancer and autoimmunity." (PMID 31001416, 2019). "Together, these data reveal a darker side of cGAS-STING signaling, as a promotor of metastasis and an inhibitor of homology-directed DNA repair, providing a possible explanation for the frequent activation of cGAS-STING signaling in cancer." (PMID 31658669, 2019). "In this minireview, we will highlight the newest insights from preclinical studies demonstrating the relevance of manipulating the cGAS-STING and RLRs-MAVS signaling pathways for cancer treatment and how these pathways are currently being targeted pharmacologically." (PMID 29686682, 2018). "Cyclic GMP-AMP (cGAMP) synthase (cGAS) stimulator of interferon genes (STING) senses pathogen-derived or abnormal self-DNA in the cytosol and triggers an innate immune defense against microbial infection and cancer." (PMID 30080846, 2018). "Comparison between drugs in these assays will require cell lines that do not undergo apoptosis during mitotic arrest or immediately after slippage, and may also depend on an intact cGAS–STING pathway, both of which vary across cancer cell lines." (PMID 29142107, 2017). "Recent research brings cGAS-STING pathway to the focus for potential treatments of cancers in that this pathway plays crucial roles in antitumor immunity and is aberrantly regulated in many cancers." (PMID 29202128, 2017). "The ability to measure 2′,3′-cGAMP levels in cells will impact our understanding about the optimal activation of cGAS that can elicit a robust anti-cancer immune response, while still not activating inflammation induced carcinogenesis." (PMID 29156566, 2017). "cGAS/STING pathway seems to be a double-edged sword in cancer, and hence it is important to understand the molecular details and spatio-temporal regulation of this pathway in the context of cancer." (PMID 29156566, 2017). "Importantly, we show that restoring the expression of cGAS or STING is sufficient to reinvigorate innate immune responses in ecDNA+ but not ecDNA− cancer cells, suggesting that cGAS is activated by ecDNA." (PMID 41509453, 2026). "The absence of the CGAS-STING1 cytosolic pathway in armadillos and pangolins suggests that they may have evolved CGAS-STING1-independent mechanisms to respond to intracellular dsDNA, which may contribute to cancer resistance because the cancer-promoting effects of CGAS-STING have also been lost." (PMID 40463121, 2025). "Thus, despite the great interest in understanding the interplay between cGAS and AIM2-dependent pathways in cancer, this review will focus on AIM2, elucidating its dual role according to cancer type, taking into consideration the current therapeutic strategies for targeting the AIM2 inflammasome." (PMID 40002808, 2025). "Finally, beyond its potential involvement in the cGAS–STING axis, SIRT7 may also influence anti-cancer immunity through additional signaling cascades that regulate inflammatory processes." (PMID 41471367, 2025). "Thus, cGAS-STING activation acts synergistically with ferroptosis by modulating iron homeostasis and amplifying oxidative stress, establishing a novel therapeutic axis for cancer-specific therapies." (PMID 40846966, 2025). "Furthermore, patients carrying HAQ/HAQ and R232H/R232H genotypes exhibited a dysfunctional cGAS-STING pathway that failed to stimulate efficient anti-cancer immunity." (PMID 41142804, 2025). "Moreover, among deadly cancers, AML cells exhibited the highest cGAS and lowest ENPP1 levels." (PMID 38413714, 2024). "Moreover, current agonists targeting cGAS–STING are mainly limited to cancer therapy, and systemic drug delivery has also not been achieved." (PMID 38525112, 2024).
cancer (continued). "Furthermore, we propose that modulating cGAS and SIRT3 activities could be potential strategies for cancer therapy." (PMID 39002667, 2024). "TET2-mediated cGAS expression may be cancer cell-specific, as VC exposure has no obvious effect on cGAS expression in endothelial cells." (PMID 38177099, 2024). "Additionally, the downregulation of TREX1 expression in senescent cells may contribute to the aberrant activation of the cGAS-STING pathway and the accumulation of cytoplasmic DNA observed in cancers." (PMID 38877472, 2024). "Notably, G4 binders such as pyridostigmine and PhenDC3 have been observed to elicit several effects, including an increase in micronuclei, activation of the cGAS-STING pathway in both human and mouse cancer cells, production of type I interferons, and activation of intrinsic immunity." (PMID 38817608, 2024). "The cGAS-STING pathway is the principle cellular cytosolic double-stranded DNA (dsDNA) sensor, leading to type I IFN release and facilitating innate immune responses to infections and cancer, and is required for efficacy of immune checkpoint blockade immunotherapy in cancer models." (PMID 38389103, 2024). "However, chronic stimulation of cGAS–STING signaling pathway may lead to abnormal inflammatory responses and even inflammation‐related cancers." (PMID 38525112, 2024). "Interestingly, the cGAS-STING signaling pathway may have different roles in inflammation and cancer." (PMID 38831059, 2024). "The cGMP-AMP synthase (cGAS)-stimulator of interferon genes (STING) pathway is a crucial component of innate immunity by responding to DNA triggers and orchestrating diverse immune responses that impact different stages of cancer development, including initiation and metastasis." (PMID 38778403, 2024). "Furthermore, activation of the cGAS/STING pathway led to natural killer cell (NK) infiltration, whereas an absence of STING in cancer cells was found to be associated with low numbers of NKs and CD8-positive lymphocytes." (PMID 39001487, 2024). "Additionally, the absence of cGAS expression in cancer cells, coupled with its presence in adjacent non-diseased tissues, implies a potential immune evasion mechanism." (PMID 38817608, 2024). "In fact, in cancer cells treated with the DNA damage agent etoposide, nuclear STING activation requires the DNA repair proteins, ataxia telangiectasia mutated and poly-ADP-ribose polymerase 1, and requires IFN-inducible protein 16, but not cGAS." (PMID 37993259, 2024). "Intracellular DNA-sensing pathway cGAS-STING, inflammasomes and pyroptosis act as critical natural immune signaling axes for microbial infection, chronic inflammation, cancer progression and organ degeneration, but the mechanism and regulation of the crosstalk network remain unclear." (PMID 38195584, 2024). "Future studies should involve the activation state and change rule of the cGAS–STING signal when two or more kinds of promoting and inhibiting effects exist simultaneously, which will help to explain the occurrence and development mechanism of inflammatory diseases and cancers." (PMID 38525112, 2024). "Through this cascade, the cGAS-STING pathway effectively translates the detection of abnormal cytosolic DNA into a potent immune response, underscoring its importance in antiviral defense, cancer immunity, and its potential role in autoimmune conditions when dysregulated." (PMID 40018367, 2024). "Furthermore, long-term use of systemicallyadministered cGAS/STING inhibitors may leave patients vulnerable toviral infections and cancer." (PMID 38563162, 2024). "Interestingly, IFNL1 expression was significantly upregulated by both doxorubicin and cisplatin in three of the cancer cell lines and did not seem to correlate with cGAS protein expression." (PMID 40012911, 2024). "Moreover, because cGAS-STING activation can lead to tumorigenesis in certain contexts, selectively inhibiting this pathway could also offer benefits in cancer prevention." (PMID 39669992, 2024).
cancer (continued). "Alternatively, it may be possible that artificial depletion of pDCs in experimental animal models potentiated the anti-cancer immune response through the activation of other damaged DNA-sensing pathways, i.e. AIM2 or cGAS-STING pathways, with DNA remaining in the TME." (PMID 37435086, 2023). "DNA DSB damaging agents, including radiation, could promote formation of micronuclei with compromised lamina allowing cytosolic exposure of dsDNA, a substrate necessary for activation of cGAS/STING pathway, IFN signaling and inflammatory response in cancer cells." (PMID 36656721, 2023). "Our data from cancer cell cultures confirm, indeed, that Pxl promotes a cGAS-STING pathway-dependent proinflammatory cascade, but they also show that Pxl treatment induces a strong upregulation of the PD-L1 protein in cancer cells in a cGAS-STING pathway-dependent manner." (PMID 36960066, 2023). "Therefore, while the cytoplasmic DNA resulting from CIN might trigger cGAS-STING and IFN signalling to activate immune surveillance, CIN+ cancers quickly adapt by alleviating the immune-activating IFN signalling to prevent immune clearance." (PMID 38067140, 2023). "cGAS-independent STING activation following the detection of nuclear DNA damage has also been described in human epithelial cells, which may be of particular relevance to cancer." (PMID 37534795, 2023). "The cGAS and STING deficiency leads to eliminated or decreased level of IFN1 response to extrinsic cytosolic DNA, which may contribute to non-inflamed cancer microenvironment." (PMID 37869102, 2023). "However, it remains unclear how cGAS-STING signaling stimulates cells to express PD-L1, which is known to mediate immune evasion of cancer cells." (PMID 36936940, 2023). "To demonstrate the inhibitory effect of PRMT1 in cancer immune surveillance through methylation of cGAS in vivo, we measured immune cell infiltration in a syngeneic mouse model of engraftment with either CT26-cGAS-WT or CT26-cGAS-KO cells after treatment with PRMT1 inhibitor MS023." (PMID 37193698, 2023). "Furthermore, the cGAS-STING pathway existed in dendritic cells (DCs) and cancer cells." (PMID 37221157, 2023). "With increasing studies providing mechanistic insights into the cGAS-STING pathway, it has been found that inappropriate activation of STING has been involved in the development of several diseases, including pulmonary fibrosis, senescence, neurodegeneration, cancer, amyotrophic lateral sclerosis." (PMID 38250078, 2023). "Therefore, modulating the activity of the cGAS-STING pathway could benefit cancer immunotherapy and inhibit cancer progression by promoting antitumor immunity and inducing SASP." (PMID 37153627, 2023). "For example, it has been recently shown that cancer cells that are chromosomally unstable are dependent on the cGAS–STING–STAT3 and non-canonical NF-κB pathway inflammatory responses to survive and that blocking IL-6 signaling targets aggressive high-CIN breast cancer cells’ growth." (PMID 37058263, 2023). "The balancing act between pro-survival STAT3 signaling and pro-death STAT1 signaling downstream of cGAS/STING signaling resulting from CIN allows cancer cells to cope when the insult is not too severe, while still allowing cells to induce apoptosis and promote immune clearance when needed." (PMID 37561163, 2023). "This intricate relationship between PARP is and the innate immune system, especially through the cGAS-STING pathway, opens new avenues for cancer treatment, combining PARP is with other immunotherapies and highlighting the critical role of the innate immune system in cancer biology." (PMID 38111536, 2023). "Moreover, cancer cells with mitochondrial dysfunction release mtDNA and the cells with STING exhibit impaired cellular fitness, suggesting an anti-tumorigenic effect of the cGAS-STING pathway in cancer." (PMID 35741087, 2022). "Thus, mtDNA from ruptured micronuclei but not cytosolic DNA stimulates the cGAS-STING pathway in cancer." (PMID 36139387, 2022).